TNF (tumor necrosis factor)
Diseases named in the same sentence as TNF in open-access papers (continued):
Sharing a sentence is not in itself a finding about the gene and the disease.
sporotrichosis (10 papers, 2013 to 2025). The commonest and least serious of the deep mycoses, characterized by nodular lesions of the cutaneous and subcutaneous tissues. "In fact, increased levels of TNF-α have been associated with the severity of sporotrichosis skin lesions in BALB/c mice." (PMID 27051673, 2016). "Only one case of sporotrichosis associated with TNF-alpha blockade was described in a patient receiving etanercept and infliximab as well as corticosteroids and methotrexate." (PMID 25755904, 2015). "Abnormal TNF-alpha regulation seems to characterize S. schenckii infection in mice, suggesting a mechanism by which TNF-alpha antagonists might predispose a person to infection by S. schenckii and consequent sporotrichosis." (PMID 25755904, 2015). "In peritoneal macrophages of mice with sporotrichosis, a correlation has been shown between the presence of TLR-4 and the secretion of both pro-inflammatory (TNF-α) and anti-inflammatory (IL-10) mediators during sporotrichosis." (PMID 34358055, 2021). "Patients with sporotrichosis showed markedly higher serum levels of TNF and IL-6 than healthy controls (HC; TNF-α: 53 ± 24 vs. 6 ± 10 pg/ml, P < 0.001; IL-6: 80 ± 42 vs. 25 ± 10 pg/ml, P < 0.001)." (PMID 32265923, 2020). "The results of our analyses of TNF and IL-6 expression in sporotrichosis patients suggest that this is so." (PMID 32265923, 2020). "In patients with sporotrichosis, TNF and IL-6 were increased in skin lesions, and markedly elevated levels in the serum were linked to disease activity." (PMID 32265923, 2020). "Taken together, our present study provides evidence that MCs exacerbate mouse and human skin S. schenckii infection and sporotrichosis by releasing TNF and IL-6." (PMID 32265923, 2020). "Expression levels of TNF and IL-6 in the lesional skin of sporotrichosis patients were markedly higher as compared to healthy control skin." (PMID 32265923, 2020). "Our analysis showed that immune-mediated inflammatory diseases commonly treated with glucocorticoids and TNF-α inhibitors were 4 times more common among hospitalizations for sporotrichosis than hospitalizations for other reasons." (PMID 27648881, 2016). "Serum levels of TNF and IL-6 were highest in patients of disseminated type sporotrichosis, followed by patients with lymphocutaneous sporotrichosis, and lowest in fixed cutaneous sporotrichosis patients." (PMID 32265923, 2020). "Immunization with rSsEno plus PGA induced a predominantly T-helper 1 cytokine pattern after in vitro stimulation of splenic cells with rSsEno: elevated levels of IFN-γ and IL-2, as well as of other cytokines involved in host defense against sporotrichosis, such as TNF-alpha, IL-6, and IL-4." (PMID 31748544, 2019). "In murine models of sporotrichosis, the peptide-rhamnomannan is involved in the anti-inflammatory response diminishing the production of IL-1β and TNF-α, and in in vitro lymphoproliferation assays have shown that it contains components with different mitogenic activities." (PMID 27051673, 2016). "In addition, opsonization has been demonstrated to enhance TNF-alpha production and fungus killing by macrophages in experimental sporotrichosis." (PMID 25755904, 2015). "It is tempting to speculate that anti-gp70-mediated phagocytosis may be essential to macrophage killing, consequently producing TNF-α to control the sporotrichosis." (PMID 24116065, 2013). "Finally, TNF and IL-6, in the context of sporotrichosis, may also be produced by cells other than MCs, for example T cells and macrophages." (PMID 32265923, 2020). "Also, a lipid antigen has been shown to decrease the production of proinflammatory cytokines such as TNF-α, IL-1β, and also IL-12 and IL-10 in experimental models of sporotrichosis; moreover, it is capable of inhibiting macrophage phagocytosis in in vitro assays." (PMID 27051673, 2016). "Taken together, our results suggest, but do not prove, that MC-derived TNF and IL-6 contribute to the pathology of sporotrichosis." (PMID 32265923, 2020).
sporotrichosis (continued). "Also, two case reports describe the development of sporotrichosis in patients treated with TNF antagonists, whereas there are no reported cases of treatment for sporotrichosis with a TNF antagonist or anti-IL-6." (PMID 32265923, 2020).
tendinitis (10 papers, 2018 to 2025). Inflammation of a tendon, usually resulting from an overuse injury. "To model tendonitis, we induced inflammation in these TDSCs by exposing them to TNF-α." (PMID 38042492, 2023). "In order to investigate the in vivo anti-inflammatory effects of SIM/PMSs on collagenase-induced Achilles tendinitis models, we monitored the mRNA levels of both pro-inflammatory cytokines (MMP-3, COX-2, IL-6, TNF-α, and MMP-13) and anti-inflammatory cytokines (IL-4, IL-10, and IL-13)." (PMID 29534523, 2018). "In addition, the local injection of SIM/PMSs into the tendons of collagenase-induced Achilles tendinitis rat models suppressed pro-inflammatory cytokines (MMP-3, COX-2, IL-6, TNF-α, and MMP-13)." (PMID 29534523, 2018). "Tenocytes in monolayer or 3D-alginate cultures in the multicellular tendinitis microenvironment (fibroblast cells) with T-lymphocytes (TN-ME) or with TNF-α or TNF-β, were kept without treatment or treated with CA to study their range of actions in inflammation." (PMID 35163616, 2022).
toxic epidermal necrolysis (10 papers, 2018 to 2024). Toxic epidermal necrolysis (TEN) is an acute and severe skin disease with clinical and histological features characterized by the destruction and detachment of the skin epithelium and mucous membranes. "The “Expert consensus on diagnosis and treatment of Stevens-Johnson syndrome/toxic epidermal necrolysis” recommends treatment options that include wound management, nutritional support, and medication with glucocorticoids, IVIG, cyclosporine, and TNF-α antagonists." (PMID 38623456, 2024). "ADRs: adverse drug reactions; DRPs: drug-related problems; HCQ: hydroxychloroquine; VAN: vancomycin; TZP: tazobactam; MEM: meropenem; ADEs: adverse drug events; HER2: human epidermal growth factor receptor-2; TNF: tumor necrosis factor; TEN: toxic epidermal necrolysis; SJS: Stevens-Johnson syndrome." (PMID 37082486, 2023).
trypanosomiasis (10 papers, 2011 to 2025). Infection with protozoa of the genus trypanosoma. "Indeed, in a model of T. brucei infection, treatment with antagonists of IL-1β and TNFα attenuated neurodegeneration, highlighting the significant role these pro-inflammatory cytokines play in trypanosomiasis-associated neuropathology." (PMID 31572363, 2019). "The parasite clearance from circulation in trypanosomiasis predominantly relies on antibody-mediated phagocytosis, the production of pro-inflammatory cytokines such as TNF-α, IL-1, and IL-6, as well as the release of nitric oxide by classically activated macrophages." (PMID 40571943, 2025). "Interestingly a line of evidences indicates that the production of TNFα is involved in the control of parasite growth but also in the development of pathogenesis in experimental trypanosomiasis." (PMID 25375156, 2014). "At the onset of trypanosomiasis, IL-10 downregulates IFN-γ and TNF-α secretion relieving inflammatory feedback." (PMID 38620045, 2024). "Since the transfer of neutrophils from Mif−/− mice into WT recipient mice did not affect TNF and liver injury, it seems that MIF production by neutrophils evidenced in this report plays a prominent, previously unappreciated role in trypanosomiasis-associated pathogenicity." (PMID 25255103, 2014).
typhoid fever (10 papers, 2014 to 2025). A bacterial infectious disorder contracted by consumption of food or drink contaminated with Salmonella typhi. "Our previous studies have shown that MAIT cells displaying distinct cytokine patterns (i.e., IFN-γ+ TNF-α+ IL-17A- positive cells) were associated with protection against typhoid fever." (PMID 39372404, 2024). "This view is consistent with the clinical observation that serum levels of pyrogenic cytokines IL-1β and TNF-α are relatively low in patients with typhoid fever compared to the levels found in patients with sepsis caused by other Gram-negative pathogens." (PMID 25136336, 2014). "This is consistent with the clinical observation that the serum levels of INF-γ and TNF-α were relatively low in patients with typhoid fever compared to other salmonellosis symptoms." (PMID 39927265, 2025). "In contrast, the production capacity of pyrogenic cytokines (TNF, IL-6) was depressed in the acute phase of typhoid fever but was restored during the convalescent phase." (PMID 25386175, 2014). "In fact, IL-1β and TNF-α production by PBMCs has been shown to be suppressed during the acute phase of typhoid fever." (PMID 25136336, 2014). "Similarly, decreased levels of inflammatory mediators, including IFN-γ and IL-17 and TNF-α and IL-6 have been reported in the serum of humans with acute typhoid." (PMID 33076485, 2020). "Moreover, significant genetic associations were reported between susceptibility or resistance to typhoid fever and HLA-DR and HLA-DQ MHC and tumor necrosis factor (TNF)-α alleles in Vietnam residents." (PMID 25386175, 2014). "In the case of typhoid fever, pro-inflammatory cytokines, including IFN-γ, IL-6, IL-10, TNF-α, and TNF, are also produced in large amounts." (PMID 40014608, 2025). "This is supported by a study showing that convalescent typhoid fever patients produced higher levels of IFN-γ, TNF-α and MIP-1β." (PMID 37207226, 2023).
ventilator-associated pneumonia (10 papers, 2014 to 2026). Serious INFLAMMATION of the LUNG in patients who required the use of PULMONARY VENTILATOR. "Elevated sTREM-1 and high sTREM-1/tumor necrosis factor α (TNF-α) ratios corresponded with poor outcomes in ventilator-associated pneumonia and septic shock." (PMID 41273150, 2026). "Combination of TLR4 and TIRAP SNPs has been described to be associated with low circulating levels of TNF-α and IL-6 in adult patients with ventilator-associated pneumonia following 1 ng/ml LPS-stimulation." (PMID 30131804, 2018). "The aim of this study was to determine the diagnostic and prognostic roles of C-reactive protein (CRP) and tumor necrosis factor-alpha (TNF-α) in differentiating between ventilator-associated pneumonia and SIRS without infectious etiology." (PMID 28469676, 2016).
acute leukemia (9 papers, 2010 to 2025). A clonal (malignant) hematopoietic disorder with an acute onset, affecting the bone marrow and the peripheral blood. "TNF-α is associated with poor clinical outcomes in acute leukemia (AL)." (PMID 35547942, 2022). "In the case of hematological malignancies, TNF-α has been found to support the cellular microenvironment promoting progression of acute leukemia and its relapse." (PMID 37232720, 2023). "The majority of the post-chemotherapy acute leukemia cases with lower TNF-a levels had complete remission (92.9%), while the majority of the post-chemotherapy acute leukemia cases with higher TNF-a levels had incomplete remission (85.3%)." (PMID 35547942, 2022). "A significant reduction in serum tumor necrosis factor-alpha level was seen in patients with acute leukemia after induction phase chemotherapy (P < 0.05)." (PMID 35547942, 2022). "In the present study, we found that serum TNF-α levels were significantly higher in acute leukemia cases than healthy controls at the time of diagnosis." (PMID 35547942, 2022). "In the present study, we conclude that a high level of TNF-α is associated with higher TLC, increased percentage of blasts, and incomplete remission in patients with acute leukemia." (PMID 35547942, 2022). "Differences in the TNF-α levels of controls and different subgroups of acute leukemia cases were found to be statistically significant (P = 0.038)." (PMID 35547942, 2022). "After the induction phase, TNF-α levels were significantly decreased in the majority of acute leukemia cases, and in the rest of the cases, high levels of TNF-α positively correlated with incomplete remission status." (PMID 35547942, 2022). "TNF-α expression levels were linked to a greater percentage of blasts in AML, extramedullary infiltration, and an unfavorable prognosis in acute leukemia." (PMID 35547942, 2022). "The aim of this study was to monitor the level of tumor necrosis factor-alpha in patients with acute leukemia at the time of diagnosis and after induction chemotherapy." (PMID 35547942, 2022). "At the time of malignancy diagnosis, plasma from patients with acute leukemia displayed higher concentrations (P<0.05) of IL-6, IL-8, IL-10, and TNF-α and lower levels of pro-LL-37 (P<0.001)." (PMID 23741421, 2013). "The plasma from patients with acute leukemia displayed significantly higher concentrations of both pro-inflammatory cytokines (IL-6, IL-8, and TNF-α) and the anti-inflammatory cytokine (IL-10)." (PMID 23741421, 2013). "Nowadays, fewer studies propose to study polymorphisms in TNFα and IL10 genes in relation to prednisone glucocorticoid in acute leukemia during childhood." (PMID 23213548, 2012). "TNF-α is involved in the progression and recurrence of acute leukemia." (PMID 41293238, 2025). "However, the study observed a significant reduction in the serum TNF-α level in patients with acute leukemia with the start of chemotherapy." (PMID 37232720, 2023). "Monitoring of tumor necrosis factor-alpha may be helpful in patients with acute leukemia in view of available antitumor necrosis factor-alpha therapy." (PMID 35547942, 2022). "In all patients with acute leukemia (n = 90) and controls (n = 10), the serum tumor necrosis factor-alpha level was measured using a Diaclone Human ELISA kit (Diaclone, Besancon, France) (solid phase sandwich ELISA) at diagnosis and after induction chemotherapy." (PMID 35547942, 2022). "Tumor necrosis factor-alpha is involved in the progression of acute leukemia and its relapse." (PMID 35547942, 2022). "Tumor necrosis factor-alpha levels were considerably reduced (P < 0.001) in the majority of acute leukemia cases after the induction phase, while high tumor necrosis factor-alpha levels were positively correlated with incomplete remission status in the remaining cases." (PMID 35547942, 2022).
acute leukemia (continued). "Considering the varied role and different expression patterns of tumor necrosis factor-alpha in acute leukemia and its clinical relevance, the present study was planned to monitor the level of tumor necrosis factor-alpha in patients with acute leukemia and its correlation with disease outcome." (PMID 35547942, 2022). "Monitoring TNF-α levels may be beneficial for patients with acute leukemia." (PMID 41293238, 2025). "The current study found that acute leukemia cases (all subgroups of AML, B-ALL, and T-ALL) had considerably higher TNF-α levels than healthy controls." (PMID 35547942, 2022). "In human acute leukemia cells (HTP-1), curcumin reduces the production of the cytokines IL-6 and TNF-α induced by Aβ protein and inhibits the phosphorylation of mitogen-activated protein kinase (MAPK) and extracellular regulated protein kinase 1/2 (ERK1/2)." (PMID 33489032, 2020). "Accordingly, serum TNF-α levels may potentially be of clinical significance in the future, in view of follow-up and the role of anti-TNF-α therapy in acute leukemia." (PMID 35547942, 2022).
adenovirus infection (9 papers, 2015 to 2020). "Third, the adenoviral RIDα protein attenuated the EGFR/NFκB signaling axis in the context of an acute adenovirus infection, and as an independently expressed transgene in cells stimulated with the pro-inflammatory cytokine TNF-α." (PMID 31425554, 2019). "Myocardial TNF-α was determined by immunohistochemistry staining in the left ventricular 7 d post-adenovirus infection." (PMID 26659007, 2015). "Local overexpression of TNF-α in heart significantly increased cardiac TNF-α levels with the highest levels achieved 4 d after adenovirus infection." (PMID 26659007, 2015). "By 1 wk post-adenovirus infection, TNF-α levels in hearts infected with adTNF-α were declining back to levels seen 2 d post-adenovirus infection." (PMID 26659007, 2015). "Additionally, TIPE2 adenovirus infection reversed the enhanced TNF-α level, whereas treatment with siTIPE2 aggravated the enhanced level of TNF-α and IL-6 in differentiated THP-1 cells under high glucose conditions." (PMID 30274259, 2018). "Furthermore, Trim29-KO BMDCs and BMDMs produced twofold to threefold more IL-6 and TNF-α in response to HSV-1 or adenovirus infection than did WT BMDCs or BMDMs at 12 or 20 h post infection." (PMID 29038422, 2017). "Interestingly, we could previously show in a model of hepatic adenovirus infection, that hepatocytes can develop an increased sensitivity towards TNFα-mediated signaling after infection." (PMID 32260486, 2020). "Caspase-8 cleavage produces a 50-kDa intracellular fragment during cell apoptosis induced by IFN-γ or TNF-α, while cellular ADAM-17 can produce an 80-kDa extracellular fragment of DSG-2 during adenovirus infection." (PMID 32457708, 2020). "The protective roles of the IL-33/ST2 axis have been reported during chronic viral infection in the liver, via promoting CD8+ T-cell responses, repressing inflammatory cytokine TNF-α, inducing type 2 innate lymphoid cells (ILC2), and protecting the liver in acute adenovirus infection." (PMID 26943125, 2016). "Importantly, no detectable changes in circulating serum TNF-α were observed at 2 d and 4 d after adenovirus infection (lower limit of detection for the assay used = 25 pg/mL)." (PMID 26659007, 2015).
allergic conjunctivitis (9 papers, 2013 to 2026). "Patients with allergic conjunctivitis demonstrate an immunological dysregulation, characterized by the low expression of IL-10 and an inverted tear IL-10/TNF-α ratio." (PMID 37020645, 2023). "Tanaka and Alfonso demonstrated that Sema3a suppressed the release of Th2-related cytokines (IL-5, IL-13 and IL-4) and inflammatory cytokines (IFN-α, IL-17 and TNF-α) but increased levels of the cytokine IL-10 in experimental allergic conjunctivitis and autoimmune arthritis models." (PMID 29975739, 2018). "Our findings demonstrate an immunological dysregulation in patients with allergic conjunctivitis, characterized by the low expression of IL-10 in circulating CD19+CD38+ Bregs subsets, and an inverted tear IL-10/TNF-α ratio." (PMID 30818819, 2019). "In sum, the activation of CD4+TLR4+T cells by the antigen and TLR induces an inflammatory microenvironment characterized by TNF-α, IL-6, and IL-4, which favors a lack of immune regulation in perennial allergic conjunctivitis." (PMID 33114004, 2020). "Our findings demonstrate an immunological dysregulation in patients with allergic conjunctivitis, characterized by the low expression of IL-10 in circulating CD19+CD38+ Bregs subsets and an inverted tear IL-10/TNF-α ratio, promoting a local pro-inflammatory microenvironment." (PMID 30818819, 2019).